BRCA1 (BRCA1 DNA repair associated)
Diseases named in the same sentence as BRCA1 in open-access papers (continued):
Sharing a sentence is not in itself a finding about the gene and the disease.
tumor (continued). "In this study, we analysed the expression profiling of a series of 14 BRCA1 tumours, which gave insights into the biological processes and molecular wiring diagrams that mediate tumorigenesis." (PMID 19826428, 2009). "This analysis demonstrates that the distribution of segment lengths within the GII-high-III subgroup is shifted towards smaller segments, whereas the tumours within the BRCA1-related subgroup display a shift towards longer segments." (PMID 19589159, 2009). "In our series the over-expression of genes related to immune response is one of the intrinsic characteristics of ESR1-negative BRCA1 tumours." (PMID 19826428, 2009). "A total of 31 genes met these criteria and, among these, two of the most differentially expressed, CD133 and MMP7, were selected for evaluation in an independent series of BRCA1 tumours." (PMID 19826428, 2009). "Tumours displaying epigenetic silencing of the BRCA1 gene were also highly enriched within this subgroup when sporadic cases were considered exclusively (Fisher's exact test P = 0.007)." (PMID 19589159, 2009). "Over-representation of transcription DNA-dependent and cell cycle-related genes and transcripts directly or indirectly regulated by ER was detected in genes differentially expressed in ESR1-positive BRCA1 tumours." (PMID 19826428, 2009). "The five familial BRCA1 tumours were combined with all the samples in our study group to subsequently re-apply the clustering procedure." (PMID 19589159, 2009). "The purpose was to examine the resulting tumour subgroups in terms of their prevalence for BRCA1 and BRCA2 abnormalities." (PMID 19589159, 2009). "Overall, the results for the independent series support the putative biological significance of the immune response in the molecular and clinical classification of BRCA1 tumours." (PMID 19826428, 2009). "Two transcription factors of this family present in our array, NFκB2 and RELB, showed over-expression in ESR1-negative BRCA1 tumours with fold changes relative to ESR1-positive tumours ranging from 3.7 to 4.1, respectively (two-tailed t-test P-values <0.05." (PMID 19826428, 2009). "BRCA1 gene-related tumours are more frequently estrogen receptor (ER) and progesterone receptor (PR) negative with a lower prevalence of human epidermal growth factor receptor 2 (HER2) overexpression or amplification." (PMID 19818148, 2009). "The main difference between the human situation and the K14cre;Brca1F5–13/F5–13;Trp53F2–10/F 2–10 mouse model is that the mouse tumours have a homozygous deletion of Brca1 exons 5–13." (PMID 19904273, 2009). "Analysis of genes differentially expressed in ESR1-negative BRCA1 tumours revealed over-representation of genes involved in the immune response and cell cycle." (PMID 19826428, 2009). "Overall, 52 genes in gene-set #2 with annotations from these processes were identified and most were over-expressed in the ESR1-negative BRCA1 tumours." (PMID 19826428, 2009). "Classification of genomic profiles through cluster analysis revealed four distinct subgroups of which two displayed high prevalence of tumours having either BRCA1- or BRCA2 abnormalities." (PMID 19589159, 2009). "The BRCA1 and BRCA2 human tumour suppressor genes are deficient in a subset of breast, ovarian and prostate cancers, and are normally required (among their other roles) for DSB repair by HR." (PMID 19319136, 2009).
tumor (continued). "All of the five familial BRCA1 tumours clustered among the tumours that constituted the previously defined subgroup of tumours enriched with BRCA1 abnormalities." (PMID 19589159, 2009). "In contrast, there was no apparent effect of reduced EZH2 levels, either by Ezh2 knock-down or DZNep treatment, in BRCA1-proficient tumor cells." (PMID 19709408, 2009). "Remarkably, all three patients had tumours that were methylated for BRCA1 as measured by both assays." (PMID 18269736, 2008). "We previously showed that tumours of BRCA1 and BRCA2 carriers aged 50 years or older differ significantly from those of younger patients." (PMID 18275599, 2008). "The BRCA1 tumor suppressor plays a major role in DNA damage, signaling, repair and cell cycle control." (PMID 18394172, 2008). "Although BRCA1 seems to be a central DNA repair component due to its many physical interactions in repair-related processes, the tumor suppressor activity is largely confined to breast and ovarian epithelia." (PMID 18197258, 2008). "An additional cluster was formed by the original Brca1 tumor A1 from our study and three of Brca1-Furth tumors previously segregated in Group II tumors of spindloid morphology." (PMID 18394172, 2008). "We will briefly review two tumour suppressor genes whose expression is altered in animals exposed to genistein: they are BRCA1 and PTEN." (PMID 18392054, 2008). "Specifically, we show that phenylbutyrate inhibits the formation of FANCD2 nuclear foci after cisplatin treatment and this inhibition correlates to a down regulation of the tumor suppressor BRCA1." (PMID 18325101, 2008). "These previously reported differences in expression of CD24 in different tumor types and in normal mouse mammary epithelium support our search for the role of CD24- cells in combination with a more established marker, CD44, in BRCA1-deficient tumors." (PMID 18241344, 2008). "BRCA1 participates in multiple cellular supercomplexes to execute its tasks and, in most of the complexes, BRCA1 exists as a RING heterodimer with BARD1 to provide ubiquitin E3 ligase activity that is required for its tumor suppressor function." (PMID 18179693, 2008). "BRCA1, located at 17q21, and BRCA2, located at 13q12-q13 both encode tumor suppressors involved in repairing double-stranded DNA breaks and maintaining genomic stability Germline BRCA1 or BRCA2 mutations are present in 10% to 15% of all EOCs." (PMID 18208621, 2008). "We measured mRNA level of ERCC1 and BRCA1 in tumor cells isolated from malignant effusions and correlated them with cisplatin and/or docetaxel chemosensitivity in vitro." (PMID 18402708, 2008). "This adds to the mounting evidence suggesting differences in molecular mechanisms involved in normal function and tumor formation in BRCA1 and BRCA2 carriers." (PMID 18542066, 2008). "BRCA2-associated tumours were also significantly more often negative for ER, PR and HER2, and detected at earlier age than sporadic tumours or non-BRCA1/BRCA2 tumours." (PMID 18275599, 2008). "The tumours included in our study were unselected for age, and about 35% of the BRCA1 tumours in our study were diagnosed at age 50 years or older." (PMID 18275599, 2008). "Selective inactivation of the BRCA1 gene in the breast results in breast hyperplasia, blunted ductal development and tumour formation." (PMID 17663789, 2007). "BRCA1 is a tumor suppressor gene responsible for hereditary ovarian cancer syndrome, and has been shown to regulate the maintenance of genome integrity, cell cycle control, apoptosis and DNA repair." (PMID 19690636, 2007). "BRCA1 is a tumor suppressor which plays a crucial role in the repair of DNA double-strand breaks, and its abnormality is responsible for hereditary ovarian cancer syndrome." (PMID 19690636, 2007). "Among these genes, the recently identified tumor-suppressor genes BRCA1 and BRCA2 contribute to a substantial portion of inherited BCa." (PMID 17915011, 2007).
tumor (continued). "Artificially increasing the expression of BRCA1 in tumour cell lines has been shown to decrease growth and induce apoptosis." (PMID 17663789, 2007). "The complex formed by BRIP1 and the BRCT repeats of BRCA1 is important for the role of BRCA1 in its DNA double strand break repair and tumour suppressor functions." (PMID 17342202, 2007). "In our basal-like tumor-derived cell lines, it has been reported that the SUM149 line has a BRCA1 mutation and SUM102 line has barely detectable transcript levels of BRCA1." (PMID 17663798, 2007). "Of the eight BRCA1 methylated tumours that displayed AI at the BRCA1 locus, five were informative for an intragenic marker and the exogenic marker." (PMID 16846527, 2006). "CGH analysis has identified a pattern of genetic imbalances that can differentiate familial BRCA1 tumours from unselected sporadic tumours." (PMID 16404418, 2006). "All the BRCA1 methylated tumours that had AI at the BRCA1 locus and were informative for AI at the exogenic and an intragenic marker displayed AI at both regions, indicating a rather large deletion at chromosome 17." (PMID 16846527, 2006). "Absent or markedly reduced BRCA1 protein expression was evident in the majority of the BRCA1 methylated tumours (9 of 13), suggesting transcriptional silencing in these tumours by epigenetic modifications." (PMID 16846527, 2006). "The BRCA1 methylated tumours were analysed for BRCA1 copy alterations by fluorescence in situ hybridisation and BRCA1 expression by immunostaining." (PMID 16846527, 2006). "A trend for AI at the BRCA1 locus was observed in the subset of BRCA1 methylated tumours (P = 0.0731)." (PMID 16846527, 2006). "This is supported by the FISH analysis, which revealed deletion of chromosome 17 in most of the BRCA1 methylated tumours that had a detectable BRCA1 deletion." (PMID 16846527, 2006). "The oncogenes c-myc, c-met, k-ras and the neoplastic progression protein-3 (Npn3) were also increased 2- to 3-fold in arsenic-induced HCC and nontumorous, normal liver from arsenic exposed mice, while the tumor suppressors BRCA1 and BRCA2 decreased 30–50%." (PMID 16507464, 2006). "Copy number alterations at the BRCA1 locus were further examined by fluorescence in situ hybridisation (FISH) in the BRCA1 methylated tumours which were also analysed for BRCA1 protein expression, histological type and tumour grade." (PMID 16846527, 2006). "DNA from the primary tumour sample was available for eight patients with BRCA1 hypermethylation and t-AML." (PMID 17047656, 2006). "AI at the BRCA1 locus was found to be strongly associated with AI at the BRCA2 locus (P < 0.0001, OR = 7.0, 95%CI = 3.0–16.4) with 26 of 124 (21.0%) informative tumours having AI at both loci." (PMID 16846527, 2006). "All BRCA1 methylated tumours were of infiltrating ductal type except for one that was of a lobular type." (PMID 16846527, 2006). "A physical deletion was detected at the BRCA1 locus in six tumours, including four with deletion of chromosome 17." (PMID 16846527, 2006). "In support of this notion, we observed ER negativity to be significantly associated with BRCA1 methylation (P = 0.0475), a well established characteristic of familial BRCA1 tumours previously reported by Catteau and colleagues and others." (PMID 16846527, 2006). "The BRCA1 methylated tumours were mainly of tumour grade 3 (7/13) and infiltrating ductal type (12/13)." (PMID 16846527, 2006). "Most of the earlier studies of the characteristics of tumours in BRCA1 and BRCA2 carriers have been based on young patients only." (PMID 15987451, 2005).
tumor (continued). "Specifically, multivariate analysis revealed age, grade and PgR negativity as the independent factors distinguishing BRCA1 tumours from familial non-BRCA1/2 tumours." (PMID 15642173, 2005). "They found that the gene expression profiles of the three tumour groups differed significantly from each other, underscoring the fundamental differences between BRCA1 and BRCA2 mutation-associated tumours." (PMID 15714204, 2005). "Tumours of BRCA1 and BRCA2 carriers aged 50 years or more differed significantly from those of younger carriers." (PMID 15987451, 2005). "The frequency of grade I and II tumours was much higher among the non-BRCA1/2 group than in the unselected control group (odds ratio 1.8, P = 0.009) or in the BRCA1 and BRCA2 groups." (PMID 15642173, 2005). "Previously, Vaziri and colleagues have reported that the tumour immunophenotype of BRCA1-carriers is influenced by the age of diagnosis." (PMID 15987451, 2005). "In BRCA1 families, tumours from patients diagnosed at over 50 years of age were surprisingly different from those in BRCA1 carriers diagnosed at under 50 years." (PMID 15987451, 2005). "Tumours of patients diagnosed at less than 50 years of age were very similar to non-BRCA1/2 tumours in the same age group." (PMID 15987451, 2005). "In a multiple regression analysis comparing non-BRCA1/2 tumours with unselected controls, grade (odds ratio 0.54, P ≤ 0.00005) and ER status (odds ratio 2.4 for negative ER status, P = 0.0006) were the independent significant factors." (PMID 15642173, 2005). "A notable feature of BRCA-1-related tumours is the possession of high mitotic rates, particularly if the mutation is at the 5′ end." (PMID 15700031, 2005). "When the frequency of abnormal expression of individual proteins was correlated with tumour grade using the Mantel-extension χ2 test for trends, there was a significant trend to an increase in abnormal BRCA1 expression with higher grade (P=0.036)." (PMID 15138484, 2004). "The clinical implication of these findings is still limited; however, it hints at differences in molecular mechanisms involved in tumour development in BRCA1 and BRCA2 carriers." (PMID 15138485, 2004). "With the recent development of BRCA1-specific antibodies, immunohistochemical analysis of tumours is now possible." (PMID 12698194, 2003). "Although BRCA1 tumours are less likely to express oestrogen receptors, heritable tumours seem histologically heterogeneous." (PMID 12177798, 2002). "This difference in the pattern of incidence rates is mirrored in the very different histopathology of tumours in BRCA1 and BRCA2 carriers, and reflects important mechanistic differences." (PMID 11857015, 2002). "Combined allelic loss of both BRCA1 and BRCA2 gene was seen in 12 of the 17 (71%) informative hereditary tumours, whereas copy number losses of both BRCA genes was seen in only 4/14 (29%) sporadic control tumours studied by FISH." (PMID 11710835, 2001). "BRCA1‐deficient cells, for instance, exhibit SL with inhibition of NAD+‐metabolising enzymes such as NAMPT and NMNAT1/2, indicating that tumours may evade PARPi by remodelling NAD+ metabolism." (PMID 41537447, 2026).
tumor (continued). "However, the activity of AURKA on its downstream substrates (P53Ser315, PLK1Thr210, and BRCA1) differed between the two tumor groups." (PMID 41515655, 2026). "It induces DNA damage and SL in BRCA1/BRCA2‐mutant tumour cells." (PMID 41537447, 2026). "For example, BRCA1 exon 11‐deficient tumours and BRCA2 mutants lacking the BRC6–8 repeats have been associated with PARPi resistance." (PMID 41537447, 2026). "Importantly, in this case of BRCA1 mutant carrier, single-cell sequencing data revealed that tumor cells had the highest levels of replication stress, and LPs had the second-highest levels." (PMID 41498327, 2026). "Altogether, these findings showed that elevated ERα signaling could enhance Smyd3 expression and cell proliferation in vitro and tumor growth in pregnant mice with G600 Brca1 mutant cells." (PMID 40157910, 2025). "This suggests its involvement in BRCA1-related pathways, contributing to tumor aggressiveness." (PMID 39997609, 2025). "In a shift towards precision medicine, FidoCure® DNA sequencing revealed mutations in BRCA1 and PTEN within the tumor, indicating that targeted therapies with PARPi olaparib and mTOR inhibitor rapamycin could be beneficial and effective." (PMID 40004231, 2025). "The activity of SCARNA2 in DNA repair could thus be generally considered a tumor suppressor role (if further confirmed), similar to the BRCA1 tumor suppressor gene." (PMID 41283331, 2025). "No somatic second hit in BRCA1 was detected in the patient’s tumor, and homologous recombination deficiency-associated features were inconclusive." (PMID 41194282, 2025). "None of the tumors demonstrating tumor regression had a BRCA1 or BRCA2 gene mutation likely to result in loss of function." (PMID 41145467, 2025). "Eight of these 11 patients with germline mutations were found to be either HRD positive or had a tumor BRCA1/2 mutation and were HRD negative." (PMID 40891252, 2025). "In tumor cells with defects in homologous recombination (HR) genes such as BRCA1/2, cells are forced to employ error-prone repair pathways like NHEJ/Alt-EJ, ultimately leading to chromosomal fragmentation and cell death—a phenomenon known as synthetic lethality." (PMID 41367875, 2025). "Additionally, increased histone deacetylase (HDAC) activity has been associated with resistance, while HDAC inhibitors can restore BRCA1 expression, thereby enhancing tumor sensitivity to PARP inhibitors." (PMID 40395324, 2025). "Moreover, the broader range of functions of BRCA1 implies that it is the more critical counterpart of the two BRCA genes, with more severe genotoxicity found in tumours associated with faulty BRCA1 than defective BRCA2." (PMID 40429877, 2025). "Preclinical studies have confirmed that ATR inhibitors (e.g., VE-821, ceralasertib/AZD6738) can restore sensitivity to PARPis in BRCA1-mutated resistant cells and demonstrate synergistic antitumor activity in HGSOC patient-derived xenograft (PDX) models, even inducing complete tumor regression." (PMID 41367875, 2025). "Trametinib, a potent inhibitor of MEK/MAPK, could reverse the expression of Smyd3 and Shcbp1 in both Brca1 mutant and WT tumor bearing mice." (PMID 40157910, 2025). "Moreover, digital droplet PCR (ddPCR) analysis was performed to assess BRCA1 copy number variation (CNV) in both the original tumor tissues and their matched organoids." (PMID 41463218, 2025).